CRP (C-reactive protein)
Diseases named in the same sentence as CRP in open-access papers (continued):
Sharing a sentence is not in itself a finding about the gene and the disease.
depression (continued). "Interestingly, depressed individuals also show exaggerated release of inflammatory mediators in response to psychosocial stressors, implying altered immunoregulation, and epidemiological studies in the UK showed that raised CRP and IL-6 predict subsequent risk of depression." (PMID 24481186, 2013). "However, similar designs have been used in many studiesdemonstrating associations between depression and inflammation, and previously wehave shown that CRP, IL6 and measures of adiposity in our sample are positivelyassociated in ways that are consistent with prior research." (PMID 24481182, 2013). "If this association between CRP and psychiatric morbidity is a consequence of depression and anxiety influencing the immune system, or if low-grade inflammation may contribute to the development of depression or panic disorder, however is as yet unknown." (PMID 18384670, 2008). "Generalized estimating equations further confirmed that elevated CRP (OR = 1.32, p = 0.001) and NLR (OR = 1.55, p = 0.001) were independently associated with depression." (PMID 40851223, 2026). "Patients with Major Depressive Disorder (MDD) (n = 170) were stratified at baseline according to high-sensitivity C-reactive protein (hs-CRP) levels into an inflammatory (hs-CRP ≥1 mg/L, n = 127) and a non-inflammatory (hs-CRP <1 mg/L, n = 43) group." (PMID 41969822, 2026). "Elevated levels of CRP (p = 0.0038), hs-CRP (p = 0.0048), and IL-6 (p = 0.0030) were identified in the anxiety group, while the depression group was characterized by reduced vitamin D levels (p = 0.0302)." (PMID 41750331, 2026). "In the univariate generalized estimating equations analysis, levels of albumin, log‐transformed CRP, NLR, and PLR were significantly associated with depression in pancreatic cancer patients (p < 0.05)." (PMID 40851223, 2026). "CONCLUSIONS: Our study reveals a significant association between inflammatory markers and depression in CCA patients, with CRP emerging as a key marker." (PMID 41618318, 2026). "Interleukin-6 (IL-6) and C-Reactive Protein (CRP) with depression were the primarily assessed inflammatory and mental health outcomes." (PMID 42031703, 2026). "Elevated levels of proinflammatory cytokines, such as interleukin-6 (IL-6), tumor necrosis factor-alpha (TNF-α), and C-reactive protein (CRP), have been observed in subsets of patients with depression and have been associated with poor treatment outcomes." (PMID 41155383, 2025). "In human studies, exposure to soil containing S. rimosus has been associated with mood enhancement, reduced stress levels, and a substantial decrease in serum C-reactive protein (CRP), a known biomarker of depression." (PMID 41209348, 2025). "In summary, our study suggests that preoperative anxiety and depression, preoperative pain, duration of tourniquet use, pain upon discharge, and postoperative C-reactive protein levels are predictive indicators of CPSP after TKA." (PMID 40103861, 2025). "Compared with healthy individuals, patients with depression exhibit significantly higher serum/plasma levels of pro-inflammatory cytokines such as IL-6 and C-reactive protein (CRP)." (PMID 39980978, 2025). "Studies highlight that CRP levels are higher in depressed patients, making elevated levels of this protein a predictor of the onset of depression in obese patients." (PMID 41373743, 2025). "Salivary CRP levels have been correlated with serum CRP in healthy adults and across cardiovascular conditions, chronic obstructive pulmonary disease, or depression; however, data on salivary CRP in chronic inflammatory conditions are still limited." (PMID 40856619, 2025). "Obese individuals who exhibit elevated levels of CRP are more likely to develop depression and anxiety." (PMID 41373743, 2025). "DM and depression were all associated with higher CRP, while carrying APOE E4 was associated with lower CRP level in both univariate and multivariate GLM (all p< 0.001) in both female and male population." (PMID 40778276, 2025).
depression (continued). "Six risk factors for predicting CPSP were identified, including preoperative anxiety, preoperative depression, preoperative pain, duration of tourniquet use, pain upon discharge, and postoperative C-reactive protein levels." (PMID 40103861, 2025). "This study explored pain- and depression-related ReHo changes in patients with AS and the association between altered ReHo and clinical features, such as TBP, the HAMD score, ESR, and CRP level." (PMID 40534742, 2025). "Among the 5579 participants, 606 (11%) met criteria for clinically significant depression, and CRP data were available for 585 of these individuals." (PMID 40943152, 2025). "We demonstrated that inflammatory markers, particularly CRP, significantly mediated the effect of composite pain scores on depression risks, indicating a critical role of systemic inflammation." (PMID 40173244, 2025). "Another meta-analysis reported that individuals with depression exhibited notably elevated blood levels of CRP, IL-6, and TNF-α relative to healthy controls, with effect sizes ranging from moderate to large (0.54 to 1.97)." (PMID 40363978, 2025). "CRP was increased in depression patients (2.55 ± 4.31 vs. 3.65 ± 5.42mg/L; p<0.001), and even higher in DM patients with depression compared with DM patients without depression (3.40 ± 5.08 vs. 4.70 ± 5.95mg/L; p<0.001)." (PMID 40778276, 2025). "For instance, the tumor necrosis factor-alpha (TNF-α) inhibitor infliximab has been shown to have antidepressant effects in treatment-resistant depression, particularly in patients with elevated levels of C-reactive protein (CRP)." (PMID 40004109, 2025). "CRP's low predictability (1.7%) within the anxiety–depression symptom network is both theoretically expected and clinically meaningful." (PMID 41048872, 2025). "For anxiety, the most relevant biomarkers were IL-8 and vitamin D. In the male group, interactions for depression occurred among vitamin D, CRP, and D-dimer, while for anxiety, the key biomarkers were vitamin D, myoglobin, and D-dimer." (PMID 40563433, 2025). "The results revealed sex-specific differences in biomarker relevance, with vitamin D, CRP, and D-dimer being the most predictive for depression in men, while IL-6, CRP, and vitamin D were significant in women." (PMID 40563433, 2025). "Pro-inflammatory proteins identified include TNF-α, IL-6, IL-1β and C-reactive protein (CRP) which have been found to be increased in individuals with depression." (PMID 39867847, 2025). "•Cross-sectional analysis at age 18 of CRP as a mediator between anxiety and/ore depression and pain-type somatic symptoms." (PMID 40823322, 2025). "Consistent with a previous study, TB patients with higher depression scores exhibited elevated CRP levels." (PMID 40927014, 2025). "In patients with cancer as well as depression and fatigue, there are also elevated circulating inflammatory cytokines, and peripheral blood interleukin (IL)-1β, IL-6, tumor necrosis factor, and CRP levels show an increasing trend." (PMID 40966684, 2025). "Some studies support the concept of a close relationship between inflammation and depression, as inflammation markers (ESR and CRP) seem to be higher in patients with RA and depression." (PMID 40095803, 2025). "Multiple studies have shown elevated levels of pro-inflammatory cytokines such as interleukin (IL)-1β, IL-6, tumor necrosis factor-α (TNF-α), and C-reactive protein (CRP) in patients with depression, particularly in those with treatment-resistant depression." (PMID 41303496, 2025). "In our study, depression was associated with an elevated ESR in RA, and anxiety was associated with an elevated CRP in PsA, although differences were small." (PMID 39504461, 2025). "Due to previous observational longitudinal and MR studies showing stronger effects of serum IL-6 compared to CRP with depression, the focus of this study is on IL-6." (PMID 39865800, 2025).
depression (continued). "Using 3 mg/L CRP as a threshold value (cut-off), approximately 40% of cases with depression had increased immune cell counts, inflammatory proteins and symptom severity scores, compared to the remaining 60% of cases without inflammation." (PMID 40141399, 2025). "Further studies should explore broader inflammatory panels, beyond fibrinogen and CRP, to better characterize these immunological signatures within psychosocial contexts and refine the mechanistic understanding of inflammation in depression." (PMID 41210298, 2025). "Decreasing low-grade, proinflammatory CRP and fibrinogen activity through enhanced physical activity and the adoption of anti-inflammatory diets (e.g., foods enriched in omega-3 fatty acids) may better regulate neuroinflammatory pathways associated with depression." (PMID 40686933, 2025). "Alongside traditional self-reported assessments of pain intensity, functional disability, quality of life, depression, anxiety and stress, the trial incorporates objective physiological markers such as cortisol, β-endorphins, substance-P, IL-6, CRP and HRV." (PMID 40510459, 2025). "Third, immune-inflammatory proteins such as CRP and immune-checkpoint proteins are also involved in depression and EC." (PMID 40547019, 2025). "We discovered a positive correlation between depression in interviews and elevated CRP and VAS pain scores in EA patients." (PMID 40837576, 2025). "Most of the research used outcome indicators such as depression and anxiety scales and CRP, IL-6, and TNF-α levels." (PMID 41010394, 2025). "The present study aims to identify core and bridge symptoms within the anxiety–depression–CRP network and to examine the structural differences in this network across groups with different insomnia severity levels in a large cohort from the UK Biobank." (PMID 41048872, 2025). "A pilot, open-label study did demonstrate efficacy and target engagement—improving depression and anhedonia scores as well as lowering mean CRP over 10 weeks of treatment." (PMID 40002494, 2025). "A previous meta-analysis reports that individuals with major depressive disorder (MDD) who experience poor sleep patterns tend to demonstrate elevated levels of CRP." (PMID 40673224, 2025). "In a similar investigation of depression, researchers correlated baseline levels of inflammatory markers (CRP, interleukins, TNF) with the severity of depression and compared their values in response to therapy." (PMID 40431406, 2025). "Several meta-analyses have consistently demonstrated elevated levels of proinflammatory markers, including IL-6, TNF-α, and CRP, in subsets of patients with depression." (PMID 41155383, 2025). "Some anti-TNF drugs, such as infliximab and etanercept, have been reported to decrease depressive symptoms, especially for patients with depression with higher CRP levels at baseline." (PMID 40699818, 2025). "Inflammatory markers (C-reactive protein (CRP) or interleukin-6 (IL-6)) can predict future depression." (PMID 40821024, 2025). "The interplay between depressive symptoms and inflammatory markers, such as C-reactive protein, further supports the notion that depression in this context represents a distinct clinical phenotype, suggesting independent prognostic significance." (PMID 41514529, 2025). "Depression and EC were found to be correlated with CRP levels exceeding 10 mg/L and with elevated serum expression, respectively." (PMID 40547019, 2025). "After controlling for gender and other pertinent variables, the subsequent investigation revealed a direct correlation between CRP and P3b latency, specifically within the cohort of depression patients exhibiting low SE." (PMID 40673224, 2025). "Those with elevated CRP levels (>5 mg/L) at baseline showed a ≥50% reduction in Hamilton Scale for Depression (HAMD) scores and a significant drop in CRP levels compared to the placebo group." (PMID 40352929, 2025).
depression (continued). "The relationship between Clostridium and FRN was confirmed by multilevel modelling analysis, controlling for depression and CRP." (PMID 40879735, 2025). "This study represents the first network analysis examining structural differences in anxiety–depression–CRP networks among groups with varying degrees of insomnia severity." (PMID 41048872, 2025). "Within the literature, there is further support for the link between the specific inflammatory biomarker, CRP, and depression." (PMID 41661985, 2025). "Serum CRP elevation is a commonly used depression marker in the general population and shows independence of lifestyle factors." (PMID 39959848, 2025). "Individuals with depression often exhibit elevated levels of inflammatory markers including IL-1β, IL-6, TNF-α, and CRP, which are directly associated with acute cardiovascular events." (PMID 41179812, 2025). "Indeed, compelling evidence supports robust connections between depression and inflammation in IA, as depression drives peripheral and central inflammation and several cytokines implicated in depression also play influential roles in IA, including CRP, TNF-α and IL-6." (PMID 38749000, 2025). "Clinicians should be aware of the high prevalence of depression in EA patients, especially patients with elevated CRP and high VAS pain scores." (PMID 40837576, 2025). "The primary aim of the current study was to investigate if inflammation, as measured by CRP levels, is a mediator of physical activity’s effect on depression at the within-subjects level in a population of older adults." (PMID 41661985, 2025). "The meta-analysis also found that consistently high levels of CRP correlate with a greater likelihood of experiencing symptoms of depression in later life." (PMID 41661985, 2025). "Anxieties, major depressive disorder (MDD), and chronic stress are all associated with systemic low-grade inflammation, which is reflected in an elevated C-reactive protein (CRP)." (PMID 40728957, 2025). "About a quarter of patients with depression exhibit inflammation, as evidenced by elevated serum C-reactive protein (CRP) levels." (PMID 40927014, 2025). "Meta-analyses have consistently demonstrated elevated levels of inflammatory markers, such as interleukins and C-reactive protein, in patients with depression, underscoring the role of inflammation in its development." (PMID 40297337, 2025). "In depression patients, females had younger age, worse VA, higher CRP levels, and lower prevalence of DR and AD compared with males (all p<0.001)." (PMID 40778276, 2025). "Salivary CRP concentrations are higher in those who report high levels of perceived stress or who exhibit clinical symptoms of anxiety and depression, according to studies." (PMID 40728957, 2025). "Three related to depression, one to deaths and the fifth related to c-reactive protein (CRP) and inflammation results." (PMID 40729394, 2025). "For depression, the strongest correlation was observed between vitamin D and CRP, consistently across both groups." (PMID 40563433, 2025). "In a tertiary sample (n = 239), serum CRP correlated with depression scores after controlling for sex and psoriasis severity." (PMID 39959848, 2025). "The association between the C-reactive protein to lymphocyte ratio (CLR) and depression was assessed through weighted logistic regression models." (PMID 40901264, 2025). "Further, increased CRP levels have been correlated with unique depression clusters or symptoms, including low energy and psychomotor aberrations." (PMID 40686933, 2025). "In a Mendelian randomization study involving candidate genes, a functional SNP in the IL-6 receptor promoter was identified, providing estimates of CRP, IL-6, and the severity of depression symptoms in a population cohort study." (PMID 40807142, 2025). "Patients with depression had significantly higher rates of anxiety, elevated CRP levels, and increased SIRI and MLR values than patients without depression." (PMID 41018179, 2025).
depression (continued). "Laboratory parameters, including total antioxidant capacity (TAC), malondialdehyde (MDA), high‐sensitivity C‐reactive protein (hs‐CRP), and psychological disorders, including depression, anxiety, and stress, were assessed at the beginning and end of the study." (PMID 40808706, 2025). "The results also showed a positive correlation between the serum concentrations of TNF-α, IL-6, and hs-CRP with depression scores before and after intervention in both groups." (PMID 39997208, 2025). "Studies examining the relationships between depression and the inflammatory markers in peripheral blood revealed a positive correlation between depression and inflammatory markers such as C-reactive protein, IL-1, and IL-6." (PMID 40243556, 2025). "Of continuous measures evaluated, depression had the largest difference in correlation between frailty and age, followed by serum glucose and C-reactive protein." (PMID 41426610, 2025). "C-reactive protein (CRP), a typical marker of systemic inflammation, is increased in patients diagnosed with depression." (PMID 40566026, 2025). "The inflammatory markers demonstrated positive relationships with neuropsychological test results because CRP and IL-6 concentrations increased with higher depression and anxiety scores." (PMID 41451009, 2025). "Critically, network analysis enables statistical comparison of structural differences, including connectivity patterns, among subgroups, allowing direct examination of how anxiety–depression–CRP relationships vary across insomnia severity levels." (PMID 41048872, 2025). "While studies have highlighted the role of inflammatory markers such as CRP and IL-6 in depression, PHR offers distinct advantages by integrating two measurable and routinely assessed parameters: platelet count and HDL cholesterol." (PMID 40606819, 2025). "Demographics, osteolytic lesions, infections, fatigue, depression, and biomarkers (albumin, creatine kinase, C-reactive protein, high-density lipoprotein, low-density lipoprotein and pro-brain natriuretic peptide) were compared in exercise vs. control cohorts." (PMID 40196920, 2025). "Increased CRP levels are related to various diseases including cardiovascular morbidity, depression, several types of cancers, and even frailty and mortality." (PMID 40565981, 2025). "Results show that patients with depression had significantly higher increases at 2 years compared to baseline for all investigated parameters (CRP—p = 0.001/Fibrinogen—p < 0.001/Interleukin-6—p < 0.001/TNF-α -p < 0.001/Cortisol—p < 0.001)." (PMID 40363978, 2025). "Other traits significantly correlated with the total depression sample, such as somatic pain, C-reactive protein (CRP), body mass index (BMI), visceral fat, lifestyle factors, and chronic diseases, showed differential patterns across subtypes." (PMID 41417750, 2025). "The capacity of both PPP‐fortified and control bread to reduce hs‐CRP and depression levels within groups suggests potential clinical significance." (PMID 40808706, 2025). "For instance, increased concentrations of peripheral biomarkers of inflammation, such as C-reactive protein (CRP) and interleukin-6 (IL-6), are associated with future symptoms of depression, and decrease with antidepressant treatment." (PMID 40494639, 2025). "Our study has identified distinct alterations in cognitive function and levels of the inflammatory marker CRP in individuals with major depressive disorder (MDD) and poor sleep quality." (PMID 40673224, 2025). "Psychosocial factors such as depression and state anxiety, along with CRP, exhibited lower importance, suggesting a lesser influence on the model’s predictions." (PMID 40259652, 2025). "Firmicutes/Bacteroidetes ratio (2.89±0.5), inflammatory markers (CRP: 4.2±4.8 mg/dL) and depression scores (Beck: 18.6±6.4) were significantly higher in mucinous neoplasm patients (p<0.05)." (PMID 41451009, 2025).